HAX1 (HCLS1 associated protein X-1)
Diseases named in the same sentence as HAX1 in open-access papers (continued):
Sharing a sentence is not in itself a finding about the gene and the disease.
breast carcinoma (continued). "HAX1 has been found to have important roles in neoplastic transformation of several types of tumors, including breast cancer, and was found to interact with urokinase-type plasminogen activator receptor implicated in tumor growth and metastasis." (PMID 27625789, 2016). "The expression of HAX-1 is increased in numerous malignancies, including lung cancer, breast cancer, CRC, lymphoma, melanoma and leukemia." (PMID 26062578, 2015). "The connection between HAX-1 nuclear location and ER status in breast cancer samples remains to be clarified." (PMID 20196840, 2010). "HAX-1 elevated levels in cancer tissues point to its involvement in neoplastic transformation, especially in breast cancer." (PMID 20196840, 2010). "Matched pairs of tumor and normal tissues were also used to determine the variations of HAX1 splicing pattern in breast cancer samples." (PMID 20196840, 2010). "Quantitative PCR was also employed to analyze the effect of estrogen on HAX1 expression in breast cancer cell line." (PMID 20196840, 2010). "HAX-1 overexpression in breast cancer samples was confirmed at the protein level by immunohistochemistry." (PMID 20196840, 2010). "HAX-1 elevated expression in breast cancer was confirmed at the protein level, by immunohistochemistry, which also revealed its nuclear localization in ER-positive tumors." (PMID 20196840, 2010). "HAX-1 up-regulation in breast cancer samples was confirmed by immunohistochemical analysis, which also revealed an intriguing HAX-1 localization in the nuclei of the tumor cells, associated with strong ER status." (PMID 20196840, 2010). "Detailed statistical analysis of these data has shown that for breast cancer and melanoma HAX1 is significantly overexpressed in subsequent stages, with higher significance for later stages." (PMID 20196840, 2010). "In this report, we present for the first time a focused analysis of HAX1 expression in several solid tumors, identifying three malignant neoplasms (breast cancer, lung cancer and melanoma) in which HAX1 is significantly up-regulated." (PMID 20196840, 2010). "The results revealed that HAX1 splicing pattern in breast cancer is indeed slightly, but recurrently different than in normal tissues." (PMID 20196840, 2010). "The results reveal statistically important HAX1 up-regulation in breast cancer, lung cancer and melanoma, along with some minor variations in the splicing pattern." (PMID 20196840, 2010). "As an alternative approach, HAX1-targeted affinity purification and mass spectrometry (AP-MS) analysis was performed independently in the two human tumor cell lines derived from cervical carcinoma (HeLa) and breast cancer (MCF7)." (PMID 33146709, 2020). "Therefore, RFS analysis was performed using KM Plotter on subgroups of breast cancer patients with different ER status, using median value of HAX1 expression to avoid high values of FDR." (PMID 31093284, 2019). "Additionally, to evaluate independent prognostic impact of HAX1 in ER+ patients relative to the well-established breast cancer prognostic indexes, including Nottingham Prognostic Index (NPI) and Adjuvant!" (PMID 31093284, 2019). "Overall survival (OS) and distant recurrence-free survival (DRFS) for 46 breast cancer patients were also evaluated by 3 different univariate and multivariate analyzes, in which the HAX1 protein expression, either cytoplasmic, nuclear, or cumulative, was assessed by IHC." (PMID 31093284, 2019). "Herein we report the results of meta-analysis of HAX1 expression, based on publicly available data, which confirms its significant overexpression in breast cancer and demonstrates copy number gain and prognostic value of HAX1 overexpression for metastatic relapse in ER+ tumors." (PMID 31093284, 2019).
breast carcinoma (continued). "Further analysis is required to confirm its prognostic value in the clinic, but assessing HAX1 protein levels and localization in primary tumor samples may become a useful tool for estimating the probability of luminal breast cancer dissemination." (PMID 31093284, 2019). "HAX1 has been found to be overexpressed in breast cancer, lung cancer, and melanoma, although the exact molecular mechanism by which overexpression of HAX1 may provide an oncogenic role needs to be evaluated." (PMID 22315598, 2012). "Immunohistochemical analysis of HAX-1 was performed on normal and breast cancer samples." (PMID 20196840, 2010). "HAX-1 nuclear localization was also observed by immunofluorescence in about 21% of cells in HAX-1-GFP-transfected MCF-7 breast cancer cell line, thus confirming IHC data, indicating that HAX-1 is present, at least to some extent, in the nuclei of breast cancer cells." (PMID 20196840, 2010). "Besides, Hax1 overexpression has been observed in several tumors, including breast cancer." (PMID 37488602, 2023). "Although there were several studies reporting HAX1 overexpression in different types of malignancies, we showed for the first time that high HAX1 mRNA levels in cancer cells could be a consequence of gene amplification, at least in breast cancer." (PMID 31093284, 2019). "Moreover, we demonstrate that HAX1 localization is important for the prediction of metastatic relapse and that cytoplasmic but not nuclear HAX1 is an independent risk factor for breast cancer metastasis." (PMID 31093284, 2019). "Therefore, HAX-1 is usually overexpressed in many malignancies, including breast cancer." (PMID 27618431, 2016). "HAX-1 overexpression detected in breast cancer, where estrogen receptor status is an obvious prognostic factor, combined with some literature data indicating possible induction of HAX1 by estrogen provided reasons to ascertain the influence of the estrogen treatment on HAX1 expression." (PMID 20196840, 2010). "SAV is a scaffold protein containing a WW domain; SAV1 was reported to interact with HAX1 and attenuated its protective role against apoptosis in MCF‐7 breast cancer cells." (PMID 28796930, 2017). "Our findings not only provide critical insights into the role of Hax1 on migration of the epithelial cell layer in breast cancer cell lines, but also unravel a novel interaction between IQGAP1 and Hax1 and demonstrate its relevance in FA dynamics and cell migration." (PMID 37488602, 2023). "HAX1 overexpression in primary breast cancer in comparison to normal breast tissues was identified at mRNA and protein level." (PMID 31093284, 2019). "Moreover, the analyses reveal significant difference between HAX1 levels in primary tumor samples between nonmetastatic and metastatic groups of patients, indicating that HAX1 may represent an independent risk factor for breast cancer metastasis." (PMID 31093284, 2019). "However, reports on the effect of Hax1 on breast cancer cell migration are not entirely consistent and somewhat contradictory." (PMID 37488602, 2023). "Thus, in this report, we have analyzed HAX1 protein levels in the primary tumor of breast cancer patients divided into metastatic and nonmetastatic groups." (PMID 31093284, 2019). "Moreover, cytoplasmic but not nuclear HAX1 demonstrated to be an independent, negative prognostic factor for breast cancer metastasis." (PMID 31093284, 2019). "Additionally, the influence of estrogen on HAX1 expression was estimated in a breast cancer estrogen-responsive cell line (MCF-7) and found not significant." (PMID 20196840, 2010).
Kostmann disease (11 papers, 2010 to 2026). "Cognitive impairment coinciding with a neurological defect and a myelodysplastic syndrome should alert physicians to Kostmann disease (HAX1 gene mutation)." (PMID 37102642, 2023). "Kostmann disease can also manifest via cognitive and neurological abnormalities in patients with deficiency in both HAX1 isoforms, with the increased risk of Myelodysplastic syndrome/leukemia." (PMID 36177048, 2022). "A diagnosis of ovarian insufficiency with severe neutropenia may indicate Kostmann disease due to HAX1 gene mutations." (PMID 37102642, 2023). "Interestingly, Kostmann disease has mixed etiology and may be caused by HAX1 mutations or mutations in ELA-2 (encoding elastase) or other genes." (PMID 33146709, 2020). "The current Kostmann disease (K-SCN) is also recognized as SCN3 and is caused by mutations in HAX1 gene, encoding HCLS1-associated protein X-1, a mitochondrial protein." (PMID 32630050, 2020). "Recently, it was observed that HAX-1 negatively regulates integrin-mediated adhesion that affects uropod detachment and neutrophil chemotaxis, a process that may be key to the pathogenesis of congenital neutropenia syndromes, such as Kostmann disease." (PMID 35379774, 2022).
colorectal cancer (8 papers, 2014 to 2026). A primary or metastatic malignant neoplasm that affects the colon or rectum. "More significantly, in colorectal cancer the increased expression of Hax-1 correlates with the lymph node metastasis and poor prognosis of the patients." (PMID 25053987, 2014). "To confirm this hypothesis, we further analyzed HAX1 expression in cells following KDM4B knockdown or overexpression in additional colorectal cancer cell lines." (PMID 27506941, 2016). "HAX1 expression was notably downregulated following KMD4B knockdown, and were also increased following KDM4B overexpression in colorectal cancer cell lines." (PMID 27506941, 2016). "Furthermore, high HAX1 ubiquitination, and increased cytoplasmic localization of TRIM23 along with elevated HAX1 levels, promotes colorectal cancer (CRC)-cell proliferation and correlates with poor prognosis in CRC patients." (PMID 38769438, 2024).
Kostmann syndrome (8 papers, 2011 to 2025). "The HAX1 gene mutation Q190X examined in this study possesses longer structure up to stop codon, compared to the other mutations W44X and R86X related to Kostmann syndrome." (PMID 40881345, 2025). "This study provides the proposed model showing abnormal degradation of JAM1 due to loss of HAX1 responsible for Kostmann syndrome complicated by periodontitis." (PMID 40881345, 2025). "Kostmann syndrome is an autosomal recessive disorder caused by a mutation of the hematopoietic cell-specific Lyn substrate 1 associated protein X-1 (HAX1) gene, and characterized by low number of neutrophils and increased susceptibility to infections." (PMID 40881345, 2025). "A previous study identified the homozygous germline mutation Q190X of HAX1 in Kostmann syndrome patients." (PMID 40881345, 2025). "Several patients with Kostmann syndrome were found to have homozygous pathogenic mutations in the HAX1 gene (which encodes HCLS1-associated protein X-1)." (PMID 40282425, 2025). "The search revealed 29 articles related to Kostmann syndrome caused by HAX1 gene mutation; they were screened, and the main clinical features of 13 cases of Kostmann syndrome with neurological abnormalities were summarized and analyzed." (PMID 33381479, 2020). "Mutations in the HAX1 (HCLS1-associated protein X-1) gene have been identified as the underlying genetic cause of the Kostmann syndrome, a subtype of autosomal recessive CN." (PMID 30891028, 2019). "It is now agreed that Kostmann's syndrome is accompanied, at least in forms due to mutations of one the two isoforms of HAX1 protein, those observed in the 'kostmann's pedigree', by neurological involvement (mental retardation and epilepsy)." (PMID 21595885, 2011). "Patients affected by Kostmann syndrome often suffer from severe periodontitis, though it remains unknown how HAX1 dysfunction causes initiation of periodontal disease." (PMID 40881345, 2025).
leukemia (7 papers, 2014 to 2025). A malignant (clonal) hematologic disorder, involving hematopoietic stem cells and characterized by the presence of primitive or atypical myeloid or lymphoid cells in the bone marrow and the blood. "The RNF217 protein is a member of RING1-IBR-RING24 (RBR) ubiquitin protein ligase family, which contains a transmembrane domain and regulates apoptosis signaling by interacting with HAX1 to promote leukemia development." (PMID 35654793, 2022). "SCN can be a pre-leukemic syndrome with evolution to leukemia recognized in patients with ELANE and HAX1 variants, as well as X-linked neutropenia (WAS)." (PMID 32066420, 2020).
melanoma (6 papers, 2010 to 2022). A malignant, usually aggressive tumor composed of atypical, neoplastic melanocytes. "Extensive apoptosis in lymphocytes and neurons, even in cardiac myocytes and melanoma cells, was observed in Hax-1-deficient mice, demonstrating the antiapoptotic role of HAX-1." (PMID 35379774, 2022). "According to Oncomine, the tumor microarray database, the expression of HAX-1 is high in many diseases like lung carcinoma, lymphoma, melanoma, and myeloma." (PMID 35602302, 2022). "Previous studies have reported on HAX-1-mediated chemotherapy resistance in T-cell leukemia and melanoma." (PMID 26062578, 2015). "Melanoma was included because of the potential role of HAX-1 in skin diseases and its reported overexpression in melanoma cell lines." (PMID 20196840, 2010). "HAX-1 is related to genesis, invasion and metastasis of many tumors, and is over-expressed in a variety of tumors such as oral squamous cell carcinoma, lung cancer, lymphoma, melanoma, leukemia, myeloma, breast cancer and hepatoma." (PMID 23531395, 2013). "It has been reported that HAX-1 silencing could induce melanoma cell apoptosis, suggesting that HAX-1 plays an important role in tumorigenesis and tumor metastasis." (PMID 23531395, 2013). "In the same report, HAX-1 was shown to be overexpressed in melanoma cell lines." (PMID 20196840, 2010).
lung carcinoma (5 papers, 2010 to 2022). "Another estimated prognostic mRNA, HAX1, has been reported to be related to lung cancers; HAX1 was overexpressed in non-small cell lung cancer; however, it was found that HAX1 was not overexpressed in normal cells." (PMID 36290366, 2022). "While HAX1 has been previously reported as being related to lung cancers, the estimation of Multi-PEN implies that the gene also has a probability of being associated with LGG." (PMID 36290366, 2022). "We tested the degradation profile of Hax-1 using a cycloheximide (CHX) chase experiment in both human lung cancer cell line H1299 and mouse neuroblastoma cell line N2a." (PMID 22827267, 2012). "In addition, Hax-1 has been found to be up-regulated in breast cancer, lung cancer and melanoma, suggesting that it also has a role in oncogenesis." (PMID 22827267, 2012). "The initial survey, performed for a cDNA panel containing samples from eight different solid tumors revealed significant HAX1 overexpression for stages III-IV of breast and lung cancer." (PMID 20196840, 2010). "The number of cases with metastatic disease for breast and lung cancer was not sufficient to calculate a relation between HAX1 overexpression and the presence of distant metastases." (PMID 20196840, 2010).
colon cancer (4 papers, 2010 to 2024). "In addition, overexpression of Hax-1 has been observed in tissues from esophageal, lung and colon cancers." (PMID 25053987, 2014). "Since our study was focused on finding a relationship between HAX1 expression levels and factors related to metastasis, such as stage, nodal status and grade of the disease, colon cancer was excluded from further analysis because of a non-significant p-level value for stages III-IV." (PMID 20196840, 2010).
glioblastoma (4 papers, 2017 to 2024). The most malignant astrocytic tumor (WHO grade IV). "In our previous work, HAX-1 was found to be overexpressed in glioblastoma tissues and cell lines, and associated with the clinicopathological characteristics and prognosis of glioblastomas." (PMID 29311840, 2017). "In our previous study, hematopoietic-substrate-1 associated protein X-1 (HAX-1), an anti-apoptotic protein, was found to be overexpressed in glioblastoma cells and tissues, which has also been reported in other malignant tumors." (PMID 29311840, 2017). "In our previous studies, we found that HAX-1 promoted cellular proliferation and attenuated apoptosis in the conditions of tumor-glioblastoma in the central nervous system." (PMID 38811533, 2024). "Another study pointed out that the abnormal expression of HAX-1 protein is vital for suppressing the apoptosis of glioblastoma cells." (PMID 35602302, 2022). "To further investigate the effect of HAX-1 on glioblastoma cell proliferation, we examined the cell cycle through flow cytometry." (PMID 29311840, 2017). "This study aimed to investigate the effect of HAX-1 in glioblastoma cells and explore the mechanism." (PMID 29311840, 2017). "HAX-1 is a well-known anti-apoptosis protein, so we investigated the effect of HAX-1 on glioblastoma cell apoptosis." (PMID 29311840, 2017). "The role and mechanism of HAX-1 in glioblastoma aroused our interest, so we knocked out the HAX-1 gene in U118 and U87-MG cell lines by CRISPR/Cas9 system, a new convenient and efficient gene compilation technology." (PMID 29311840, 2017). "These phenomena indicate that HAX-1 influences the proliferation and apoptosis of glioblastoma cells U118 and U87-MG." (PMID 29311840, 2017). "Through these experiments, we demonstrated for the first time that HAX-1 could regulate cell proliferation and apoptosis of glioblastoma cells by affecting the activation of the Akt1 signal pathway via interaction with Hsp90." (PMID 29311840, 2017). "The current study was designed to test this hypothesis by altering the expression of HAX-1 in glioblastoma cell lines U118 and U87-MG." (PMID 29311840, 2017). "HAX-1 can inhibit apoptosis by multiple pathways, so HAX-1 may have an important role in the survival of glioblastoma cells in hypoxic-ischemic environments, which still remains unclear." (PMID 29311840, 2017). "However, the effect and mechanism of HAX-1 in glioblastomas remains unknown." (PMID 29311840, 2017). "In this study, we established HAX-1 knock-out U118 and U87-MG cell lines, and used them to explore the role of HAX-1 in glioblastoma cells." (PMID 29311840, 2017).